IL10 (interleukin 10)
Diseases named in the same sentence as IL10 in open-access papers (continued):
Sharing a sentence is not in itself a finding about the gene and the disease.
tumor (continued). "Upon histological analysis, extensive necrotic areas of tumor in MBT-treated samples were INF-γ to interleukin 10 level ratio (INF-γ/IL-10) revealed a Th1 shift in the tumor microenvironment of MBT-treated tumors." (PMID 33810617, 2021). "M2 macrophages indirectly promote tumor cell growth by secreting interleukin-10 and transforming growth factor-β while inhibiting immune response cells in the microenvironment." (PMID 34458140, 2021). "Flow cytometric analysis showed increases in regulatory T cells (Tregs) in lymph nodes in CCL17 TG mice with high mRNA levels of IL-10 and Foxp3 in tumors, suggesting that Tregs attenuated tumor immunity." (PMID 33670758, 2021). "Tumor cells secrete immunosuppressive cytokines such as IL-10, or immune cells, such as regulated T cells and M2 macrophages in the TME, inhibit the activity of antitumor effector cells due to their immune inhibition function." (PMID 34682815, 2021). "In pancreatic tumors, inhibition of the Bruton’s tyrosine kinase (BTK) signaling pathway reduces IL-35 and IL-10 expression and decreases i35-Breg cell function, suppressing tumor cell growth." (PMID 34093586, 2021). "Th2 cells secrete interleukin (IL)-4 and IL-10, which recruit immunosuppressive cells to negatively regulate the Th1 anti-tumor response, and support tumor growth and metastasis." (PMID 33639614, 2021). "M2 macrophages meanwhile exert an immunosuppressive phenotype, favoring tissue repair and tumor progression; they secrete anti-inflammatory cytokines such as IL-10, IL-13, and IL-4 along with expressing CD206." (PMID 34917263, 2021). "The relevance of these findings to the clinic is also unclear as these experiment use highly immunogenic tumour antigens and involved a peritumoral mode of delivery for IL-10-Fc." (PMID 34621543, 2021). "IL-10 is an anti-inflammatory cytokine with a dual effect on tumor progression that depends on the specific tissue environment to exert anti-tumor immune response or promote tumor immune escape." (PMID 34625124, 2021). "STAT3 and ERK are activated by common interleukins in a tumor microenvironment like IL-10, TNF-α, and IL1β." (PMID 34177892, 2021). "Tumour-promoting M2 macrophages are induced in tumours by specific cytokines including interleukin-4 (IL-4), IL-10, IL-13 and macrophage colony-stimulating factor (M-CSF)." (PMID 34062862, 2021). "Tumor cells secrete DAMPs for the differentiation of naive T cells into Tregs and secretion of cytokines such as IL-10 and TGF-β to promote the formation of an immunosuppressive microenvironment." (PMID 34638242, 2021). "M2 macrophages secrete the anti-inflammatory interleukin-10 (IL-10), which supports tumor progression." (PMID 34830787, 2021). "Tumor-infiltrating LY6G MDSCs from orthotopic liver tumors treated with sorafenib significantly induced CD4+T cells expressing IL-10 and TGF-β and down-regulated the cytotoxic activity of CD8 T cells." (PMID 34869376, 2021). "IL10 that strongly inhibits cell-mediated immunity and inflammation, and promotes plasma cell differentiation, is known to be produced by cHL tumor cells." (PMID 35008292, 2021). "They found that ACT of tumour antigen-specific PMEL CD8+ T cells with IL-10-Fc enhanced tumour infiltration of TILs and increased the number of CD8+ T cells with minimal impact on other lymphocytes or myeloid cells." (PMID 34621543, 2021). "The protein levels of NF-κB and phospho-NF-κB and the mRNA expression of Il10 and Infg were increased in the tumor tissue of the P. anaerobius-colonized mice." (PMID 33578830, 2021). "In vivo, the block of A2BARs increases CD8+ T cells, natural killer cells, and the production of TNF-α and IFN-γ in the tumor microenvironment, accompanied by reduced levels of IL-10, VEGF, and angiogenesis." (PMID 34299305, 2021). "In tumor biopsies, all groups showed a significantly lower expression level of the IL-10 peptide group (P < 0.0001)." (PMID 34282215, 2021).
tumor (continued). "Our findings demonstrate that inhibition of p-STAT3 signaling by Stattic decreased IL10-promoted tumor growth and tumor volume." (PMID 33500726, 2021). "Conversely, the PTX-induced upregulation of the M2 marker gene, Il10 in CD11b+ myeloid cells from 4T1 tumor-bearing mice treated was dramatically reduced by the administration of the HO-1 inhibitor." (PMID 33809707, 2021). "IL-10 was also shown to promote CD8+ T-cell anti-tumor activity and expansion of intratumoral CD8+ T-cells." (PMID 34372571, 2021). "Both cell types can be further polarized towards a M2 phenotype, through different factors (such as IL-10) or induced by the presence of tumour cells." (PMID 34572836, 2021). "In these immunosuppressive marker genes, PD-L1, TGFB1, and IL10 were significantly correlated with FUCA2 expression in most tumor types." (PMID 34745134, 2021). "Classically activated macrophages (M1) produce high levels of IL-12 and low levels of IL-10 and promote tumor initiation, whereas alternatively activated macrophages (M2) are characterized by low IL-12 and high IL-10 production and promote tumor progression." (PMID 33854960, 2021). "TGF-β can also induce tumor cells to overexpress IL-10 to activate Th2 while inhibiting Th1 immune activity, thereby breaking the balance of Th1 / Th2, and ultimately suppressing immune killing of tumor cells." (PMID 33391402, 2021). "The expression of four CAF-specific markers correlated positively with that of CD68, CD163, MRC1, IL10, and TGFB1, which are markers that characterize tumor-associated macrophages (TAMs)." (PMID 33799788, 2021). "The expression of Granzyme B (GzmB) has been shown to be a major mechanism for IL-10 mediated anti-tumor T cell responses in a mouse tumor model." (PMID 34769278, 2021). "IL-35 regulated the tumor microenvironment together with negative regulators (e.g., IL-18BP and IL-10), which played a key role in tumor immune escape, and promoted tumor progression and metastasis." (PMID 33777929, 2021). "The M2d subtype, also known as tumor‐associated macrophages (TAMs), secretes TNFα, IL‐6, IL‐10, TGFβ, and VEGFA to promote tumor progression." (PMID 34136188, 2021). "IL-10 is an anti-inflammatory cytokine and interestingly synergizes with IL-12B to regulate inflammation in tumor models." (PMID 34512619, 2021). "Via the release of CCL2, TAMs recruit further myeloid populations to the tumor, and through the released factors IL-10 and TGF-β, mitigate induction of immunosuppressive MDSC and suppression of APC recruitment and function." (PMID 33917501, 2021). "LAG-3 positive Tregs occur in primary tumours, in lymphocytes of tumour-invaded lymph nodes, and in lymphocytes infiltrating visceral metastases, and produce immunosuppressive cytokines, IL-10 and TGF-β." (PMID 34968365, 2021). "IL-10 is a versatile cytokine that allows malignant cells to evade immune regulation and promote tumor growth." (PMID 33391402, 2021). "Based on previous studies, CD4+ T cells are related to the production of effective antitumor immune responses, while Treg cells inhibit the antitumor immune microenvironment by secreting cytokines IL10 and TGFβ in the tumor microenvironment." (PMID 34220801, 2021). "In many cancer types, it is known to aid in tumour progression (HIV-positive cervical cancer), while in gastric adenocarcinoma and prostate cancer cases, diminished levels of IL-10 are found to be a high-risk factor." (PMID 34336101, 2021). "Immune suppressive cytokines, such as TGFβ and IL-10, are a major obstacle in generating effective anti-tumor immunity." (PMID 33936033, 2021). "In contrast, the PTX-induced upregulation of the M2 marker gene, Il10 in CD11b+ myeloid cells isolated from 4T1 tumor-bearing mice was abolished by administration of ZnPP." (PMID 33809707, 2021). "As indicated from many of the mentioned studies, the tumor-promoting effect of B cells is mainly attributed to the regulation of B cells that secrete IL-10 as their immunosuppressive function." (PMID 34235074, 2021).
tumor (continued). "The tumor microenvironment (TME) promotes the generation of Treg cells that mediate IL-10 dependent immune suppression in a cell-contact independent manner." (PMID 34675933, 2021). "Interleukin-10 (IL-10) is an immunosuppressive cytokine that is thought to promote tumor ‘immune escape’ by diminishing anti-tumor immune response in the TME." (PMID 34638432, 2021). "The abundance of M2-like macrophages in the hypoxic TME facilitates tumour progression through the production of high levels of IL-10, and by promoting angiogenesis, invasion and metastasis." (PMID 33923305, 2021). "Accordingly, serum levels of anti-tumorigenic cytokines (TNF-α and IL-17) were decreased and the serum concentration of immunosuppressive IL-10 was increased in MSC-treated tumor-bearing animals." (PMID 34830312, 2021). "Firstly, IL-10-Fc was shown to reduce B16F10 tumour burden on its own and to synergize with ACT of PMEL CD8+ T cells." (PMID 34621543, 2021). "Further studies found that histone deacetylase 11 (HDAC11) and alarmin high mobility group box 1 (HMGB1) are key negative regulators of IL-10 transcription in MDSCs, indicating a promising therapeutic strategy for enhancing anti-tumor immunity." (PMID 35004667, 2021). "Th1 cells secrete cytokines IFN-γ, TNF-α, IL-12, which play an essential role in tumor immunity, and IL-4, IL-6, and IL-10 are cytokines secreted by Th2 cells, which can inhibit the secretion of cytokines by Th1 cells and promote humoral immunity." (PMID 35071004, 2021). "Our results demonstrated that atovaquone treatment resulted in 13% and 40% reduction of TGF-β and IL-10 levels, respectively, indicating a reduction of immunosuppression in the tumor microenvironment." (PMID 34068008, 2021). "In contrast, Th2 cells secrete anti-inflammatory cytokines, such as IL-4, IL-5, and IL-10, and are tumor-promoting." (PMID 34290984, 2021). "But IL-10 is also able to produce anti-tumor effects by inhibiting angiogenesis factors and improving the proliferation and cytotoxicity of CD8+T cells in the TME." (PMID 34625124, 2021). "The highest levels of serum IL-6, IL-10, and CRP were observed for the group administered with zotarolimus combined with 5-FU, and this was associated with the highest inhibition rate of tumor growth." (PMID 34361836, 2021). "IL-10 derived from TAM-M2 has been implicated in the suppression of NK cells and cytotoxic T lymphocytes, thereby reducing the tumour cells to be killed." (PMID 34141479, 2021). "IL10, a powerful anti-inflammatory mediator secreted by tumor cells and almost all immune cells, possesses a dual role." (PMID 34205944, 2021). "Correspondingly, flow cytometry analysis showed that the expression levels of IL-10 and PD-1 in B cells were higher when B cells were co-cultured with tumor-derived EVs." (PMID 35059436, 2021). "Kyn activates the aryl hydrocarbon receptor (AhR) which contributes to cancer immune escape since it promotes an immunosuppressive tumor microenvironment by an increase of IL-10, Treg cells and suppressing immune activation cells." (PMID 33466323, 2021). "In contrast, the CD209+ CD83− NTLS-DC subpopulation has an immunosuppressive phenotype and develops under the stimulation of various tumor-derived factors, including IL-10, TGF-β, prostaglandin E2 (PGE2), and chemokines." (PMID 33746989, 2021). "Conversely, high salt treatment decreased the expression of anti-inflammatory IL-10 cytokine from DLNs, tumor splenocytes and non-tumor splenocytes, as compared to respective equimolar mannitol treatment." (PMID 33918403, 2021). "These T cell population and activation states have been primarily attributed to the relatively high concentrations of anti-inflammatory cytokines (i.e., TGF-β, IL-10) secreted by tumor cells as well as GAMs." (PMID 34177918, 2021). "Low infiltration of CD56+ and CD28+ cells, as well as high expression of IL-10 in tumor tissue, were related with increased invasiveness of NFPAs." (PMID 34257554, 2021).
tumor (continued). "Conversely, M2 macrophages are stimulated by the type 2 T helper cell (Th2) cytokines (IL-4, IL-10, and IL-13) and exhibit pro-tumorigenic functions, including tissue remodeling and tumor progression." (PMID 33916915, 2021). "In the later stages of tumor progression, the tumor microenvironment becomes rich in growth factors and mediators such as IL-4, IL-10, and TGF-β, which mediate macrophage polarization and acquire the M2-like phenotype." (PMID 34283044, 2021). "In combination with the αCD28 BiMAb we also observed a reduction of tumor cell lysis by IL-10/TGF-β, however, this decrease was significantly less pronounced compared to αCD3 BiMAb alone." (PMID 34484225, 2021). "IL-10 interferes with the antitumor activity of the immune system by inhibiting antigen presentation in both antigen presenting cells and tumor cells and inducing T cell anergy." (PMID 33578830, 2021). "CM collected from LECs treated with IL-10 stimulated tumour cell chemotaxis to an even greater extent than CM obtained from untreated LECs." (PMID 33484377, 2021). "On the other side, cancer models have shown that IL10 also induces intratumoral antigen presentation with infiltration and activation of tumor-specific cytotoxic CD8 T cells expressing IFNγ and granzymes." (PMID 34447383, 2021). "Studies have also found that IL-10 is associated with advanced disease, with lesional skin from the tumor stage showing higher expression of IL10 mRNA, compared with patch and plaque stage MF." (PMID 34204115, 2021). "We show here that their reprogramming towards an M2-like phenotype (tumor-supportive) with IL-10 leads to an increase in leukemic cell survival." (PMID 35008174, 2021). "IL-10 has direct anti-tumor and anti-macrophage toxicity in vitro, reinforcing its effectiveness in mediating anti-tumor immune responses." (PMID 33912464, 2021). "Under the same study, an experiment on C57BL/6 mice with lycopene (40 mg/kg) administered intraperitoneally for 3 days resulted in the reduction of tumor volume, weight, IL-4, IL-10, gene expression of DMNT3a and methylation levels of promoters (IRF1, IRF7)." (PMID 34202203, 2021). "Constitutive STAT3 activity in tumours increases the production of pleiotropic factors, such as IL‐10 and VEGF, which inhibit DC maturation via STAT3 signalling." (PMID 33382511, 2021). "Expression of PD-L1 on the surface of tumour cells allows for engagement with PD-1+ T cells, resulting in T cell dysfunction by exhaustion, anergy, apoptosis and IL-10 expression." (PMID 34062862, 2021). "Substantial reductions in suppressive cytokines, including CCL2, CCL17, CCL22 and IL-10, were also noted and were associated with reduced CD4+ CD25+ Foxp3+ Treg recruitment in the tumour." (PMID 33513866, 2021). "M2 macrophages release substantial VEGF-A and IL-10 to support tumor cells proliferation mainly by oxidative phosphorylation." (PMID 34368156, 2021). "The pro-oncogenic effects most commonly mentioned for IL-10 are that IL-10 reduces the antitumor immune response in the tumor microenvironment, thus helping tumor cells to evade the effects of immune cells and stimulates angiogenesis." (PMID 34443443, 2021). "Lastly, IL-10-Fc was also found to synergize with anti-PD1 ICB immunotherapy in a mouse CT26 colorectal tumour model leading to tumour eradication and durable immune responses." (PMID 34621543, 2021). "Previous studies have reported that IL-10 mediates the immune response against the tumor and also inhibits metastasis in a mice model." (PMID 33912464, 2021). "In vitro analysis highlighted an immunosuppressive cytokine profile in tumour involved lymph nodes consisting of higher levels of IL6, IL10, and TNFα released under stimulation, while IFNγ release was high in cells from tumour free lymph nodes." (PMID 34640541, 2021). "We detected significant inverse relationships between IL10 levels and patients with tumours (P = 0.0124)." (PMID 34872566, 2021).
tumor (continued). "In summary, our work unravels an IL-6-regulated cellular mechanism that controls Mφ-mediated tumor immunity through IL-10 and Stat3/HIF-1α/CD40 expression." (PMID 34103524, 2021). "Tumor cells and their microenvironment usually express cytokines (such as IL-10 and TGFβ) with immunosuppressive functions, which inactivate effector immune cells and recruit immunosuppressive cells to the tumor." (PMID 34901031, 2021). "A study on gastric tumor tissue showed that IL-10 levels were elevated compared to normal tissue and that it stimulates tumor proliferation and migration and inhibits apoptosis." (PMID 34832887, 2021). "We and others have found that BI-ALCL tumor cells exhibit an activated CD4+ transcriptional profile with T regulatory features due to an IL10-, IL6-, IL13- and Eotaxin-rich cytokine microenvironment." (PMID 34944796, 2021). "We provide evidence of an IL-10 producing response to a citrullinated peptide presented by B16 tumours suggesting regulatory T cell repertoires exist to citrullinated peptides." (PMID 34858415, 2021). "Collectively, the immunosuppressive and tumor-promoting effect of IL-10 is related to M2 polarization of macrophages." (PMID 34625124, 2021). "On the other hand, IL-10 secretion by IgA ASC has been shown to suppress anti-tumour responses of CD8 T cells and hence is detrimental in both, prostate and liver tumour microenvironments." (PMID 33936114, 2021). "Both IL-10 and IL-15 have significant effects on tumor volume shrinkage as well as on prolonging mice survival." (PMID 33912464, 2021). "Following RFA, a decrease in TGF-β, which acts as a pro-oncogenic cytokine, in IL-10, which normally stimulates tumor progression and inhibits cytotoxic T cells and NK cells, and in Tregs levels, has been reported." (PMID 34830949, 2021). "On day 10 of tumor development, the serum IL-10 concentration increased in tumor-bearing rats by a factor of 1.7, to 55.00 ± 17.30 pg/mL, compared with 33.26 ± 4.27 pg/mL in intact rats (control)." (PMID 34443443, 2021). "Neutrophils secrete factors that stimulate tumor progression, such as interleukin-2 (IL-2), interleukin-6 (IL-6), interleukin-10 (IL-10), tumor necrosis factor α (TNF-α), and vascular endothelium growth factor (VEGF)." (PMID 34830745, 2021). "Whiteside and co-Workers affirm that once exposed Treg with tumour Exo, these immunosuppressive cells show enhanced suppressive functions and exhibited a greater expression of IL-10, TGF-β, Fas Ligand, CTLA4, granzyme B (GrB) and perforin." (PMID 34943819, 2021). "M2 TAMs cause immunosuppression and promote tumor progression by releasing various matrix metalloproteinases (MMP-7 and MMP-9) and increasing the levels of IL-10, VEGF, IL-12, TGF-β and fibroblast GF." (PMID 34834282, 2021). "Increased tumour-infiltrating IL-10-producing regulatory B cells also correlated with immune evasion in patients with gastric cancer." (PMID 34732892, 2021). "IL10 levels are increased in K-ras mutant mouse tumors and gene knock down inhibited tumor development while decreasing levels of infiltrating macrophages and Treg lymphocytes." (PMID 33632299, 2021). "Once within the TME, Tregs are subjected to favorable conditions which allow for increased viability and expansion, in addition to promoting the transition of other T cells into Tregs via cytokines such as tumor-derived IL-10 and TGF-β." (PMID 34571905, 2021). "In terms of mechanism, exosomal miR-214 inhibits the expression of phosphatase and tensin homolog (PTEN) in T cells and induce Tregs to secret IL-10, finally promoting tumor growth." (PMID 34616851, 2021). "The anti-inflammatory properties of intestine macrophages depend on IL-10 and TGF-β secretion in colonic mucosa and CD200R stimulation can suppress activity and IL-10 production of anti-inflammatory tumor-associated myeloid cells." (PMID 34069671, 2021).